LINC02914 (long independently transcribed non-coding RNA 2914)
Description:
May play a role in the flagellum biology.
Synonyms: C14orf177; FLJ25773
Gene: Long non-coding RNA gene on chromosome 14 (98,711,613 to 98,717,761, forward strand). Ensembl gene ENSG00000176605.
Subcellular location: Cytoplasm; Nucleus; Cell projection, cilium, flagellum
Diseases named in the same sentence as LINC02914 in open-access papers:
LINC02914 is named in the same sentence as 2 diseases in open-access papers, as found by Europe PMC text mining. Sharing a sentence is not in itself a finding about the gene and the disease. The quoted sentences say what the papers report.
Alzheimer disease (1 paper, 2025). A progressive, neurodegenerative disease characterized by loss of function and death of nerve cells in several areas of the brain leading to loss of cognitive function such as memory and language. "LINC02914 has been less studied in the context of lipid metabolism, hypertension, or Alzheimer’s disease pathology, highlighting the need for additional functional studies to map its precise role in human diseases." (PMID 40564227, 2025).
LINC02914 also shares sentences with these, for which no sentence is quoted: Hypertension (1 paper).